IGHV3OR16-8 (immunoglobulin heavy variable 3/OR16-8 (non-functional))
Synonyms: IGHV3/OR16-8; IGHV3OR168
Gene: Immunoglobulin variable (V) gene on chromosome 16 (33,009,175 to 33,009,620, forward strand). Ensembl gene ENSG00000271130.
Gene Ontology:
Molecular function: antigen binding
Biological process: immunoglobulin mediated immune response
Cellular component: extracellular region; plasma membrane
Homologues: Paralogues in human: IGHV3OR16-17 (98% identical), IGHV3-11 (88% identical), IGHV3-23 (84% identical), IGHV3-21 (83% identical), IGHV3-48 (83% identical), IGHV3-66 (83% identical), IGHV3-74 (83% identical), IGHV3-43 (81% identical), IGHV3-53 (81% identical), IGHV3-7 (81% identical), IGHV3-20 (80% identical), IGHV3-35 (80% identical), and 65 more.